RN7SKP287 (RN7SK pseudogene 287)
Gene: Miscellaneous RNA gene on chromosome 11 (43,435,132 to 43,435,397, reverse strand). Ensembl gene ENSG00000252355.
Homologues: Orthologues: chimpanzee 7SK (99% identical), mouse Gm55618 (53% identical). Paralogues in human: 7SK (61% identical), RN7SKP162 (61% identical), RN7SKP160 (60% identical), RN7SKP76 (60% identical), RN7SKP118 (60% identical), RN7SKP25 (60% identical), RN7SKP128 (59% identical), RN7SKP178 (59% identical), RN7SKP269 (59% identical), RN7SKP9 (59% identical), RN7SKP103 (59% identical), RN7SKP185 (59% identical), and 284 more.